MTOR (mechanistic target of rapamycin kinase)
Diseases named in the same sentence as MTOR in open-access papers (continued):
Sharing a sentence is not in itself a finding about the gene and the disease.
myocardial infarction (80 papers, 2014 to 2026). Gross necrosis of the myocardium, as a result of interruption of the blood supply to the area, as in coronary thrombosis. "Suppressing the mTOR signal can reduce the area of myocardial infarction (MI), improve cardiac function, and lower the risk of atherosclerosis." (PMID 39634266, 2024). "Primed B cells with damage-associated molecular patterns (DAMPs) after myocardial infarction could be decreased by mTOR inhibition so that the progression of atherosclerotic plaques fueled by primed B cells is hampered." (PMID 35845058, 2022). "In acute myocardial infarction induced by ischemia and hypoxia, BMSCs inhibit autophagy through mTOR signaling pathway to improve myocardial damage." (PMID 40000609, 2025). "In ischemia-reperfusion injury (IRI) and myocardial infarction, the role of mTOR in cell death becomes evident through its modulation of apoptosis, necrosis, and ferroptosis." (PMID 40734978, 2025). "In the context of aPL-associated coronary artery disease, stents coated with mTOR inhibitors have been suggested as a potential treatment for patients with APS and myocardial infarction." (PMID 39830377, 2024). "Lithium facilitates physiological ventricular remodeling post-myocardial infarction by activating the PI3K/AKT/mTOR signaling pathway, suggesting potential implications for heart attack therapeutics." (PMID 38169754, 2024). "MiR-22 inhibits myocardial fibrosis in rats with myocardial infarction by targeting the PTEN/Akt/mTOR signaling pathway." (PMID 38705985, 2024). "mTOR inhibitions has been shown to reduce the infarction size and left ventricular remodelling following myocardial infarction in an animal model." (PMID 38661439, 2024). "1α,25(OH)2D3 plays a protective role in acute myocardial infarction through autophagy induced by the PI3K/AKT/mTOR pathway." (PMID 36901794, 2023). "The mTOR signaling pathway plays an important role during myocardial infarction and it regulates cellular function in a variety of ways." (PMID 36769107, 2023). "Experiment has further determined that TGC reduced the area of myocardial infarction and increased the left ventricular ejection fraction, by regulating autophagy-related proteins in the mTOR pathway to inhibit cell apoptosis." (PMID 36789620, 2023). "Potential mechanisms explaining the relationship between elevated BCAAs levels and risk of CVD include activation of the mammalian target of rapamycin (mTOR) signaling, which leads to exacerbated cardiac dysfunction, and remodeling in myocardial infarction." (PMID 35807835, 2022). "Curcumin is an anti-oxidant while Salidroside in Rhodiola can regulate SOD levels and protect Lipopolysaccharide-induced myocardial infarction through the ROS mediated PI3K/Akt/mTOR signaling pathway." (PMID 35935647, 2022). "Rapamycin, the prototypical mTOR inhibitor, was shown in hypertrophy experiments in mice to reduce damage following ischemia-reperfusion injury and myocardial infarction by modulating apoptosis, ERK, and NO signaling." (PMID 35845058, 2022). "On the other hand, in myocardial wound healing reduced mTOR signaling elevated autophagy, which improved left ventricular remodeling following myocardial infarction." (PMID 35845058, 2022). "Reduced mTOR leads to an increase in the number of Tregs that have mitigating functions in atheromata and myocardial infarction as described." (PMID 35845058, 2022). "Emerging evidence suggests that mTOR can also operate as a relevant target to alter the outcome of a myocardial infarction." (PMID 35845058, 2022). "In experimental models, inhibition of mTOR signaling reduces myocardial infarct size, enhances functional remodeling, and lowers the overall burden of atheroma." (PMID 35845058, 2022). "(Maodongqing), protects against myocardial injury after myocardial infarction by inhibiting the AMPK/mTOR signal pathway and excessive autophagy." (PMID 34926607, 2021).
myocardial infarction (continued). "Tong-Guan Capsule promotes cardiomyocyte autophagy in the myocardial infarction mouse model by activating Sirt1 and down-regulating the mTOR/P70/S6K/4EBP1 pathway." (PMID 34926607, 2021). "Spermidine‐enhanced autophagic flux improved cardiac dysfunction by activation of AMPK/mTOR signalling pathway in myocardial infarction." (PMID 32424968, 2020). "Second, we demonstrated for the first time that mTOR inhibition by rapamycin reduced myocardial infarct size, hindered cardiomyocyte apoptosis and preserved cardiac function in aortic‐banded mice following MI/R." (PMID 29314656, 2018). "Inhibition of the mTOR signaling pathway has been reported to protect the heart against pathological damage including myocardial infarction and hypertrophy." (PMID 30050390, 2018). "In the context of CVDs, mTOR activation in immune cells like macrophages and neutrophils can lead to the release of pro-inflammatory cytokines, amplifying the tissue damage and necrosis seen in conditions like myocardial infarction and aortic dissection." (PMID 40734978, 2025). "For instance, the Akt3/mTOR signaling pathway regulates apoptosis induced by myocardial infarction via autophagy, indicating that Akt3 could regulate autophagy." (PMID 37511199, 2023). "Inhibiting mTOR signaling was cardioprotective during myocardial infarction in rats." (PMID 36769107, 2023). "To date, the CLEVER-ACS clinical trial (NCT01529554) is the only study that aims to translate the idea of targeting mTOR activity in myocardial infarction into the clinical setting while laying a specific focus on the immunomodulatory function of mTOR inhibition." (PMID 35845058, 2022). "It is speculated that miR-99a may increase autophagy and inhibit apoptosis via inhibition of the mTOR signaling pathway, thus improving cardiac function and survival rate in mouse models of myocardial infarction." (PMID 35370737, 2022). "In addition, also natriuretic peptides, which are elevated after myocardial infarction, were recently identified to promote white adipocyte browning via mTOR." (PMID 36388122, 2022). "Within this constellation, mTOR inhibition in myocardial infarction could interrupt the vicious cycle of constant mTOR activation and accelerated immune response to ameliorate myocardial wound healing in the critical days after the incident." (PMID 35845058, 2022). "Limiting NKT cell activity by mTOR inhibition could beneficially limit inflammatory response and cytotoxicity in both myocardial infarction and atheroma." (PMID 35845058, 2022). "Of note, the therapy duration must be considered, as extended mTOR inhibition, for example, may increase fibrosis in myocardial infarction via persistent elevated levels of pro-fibrotic cytokines (e.g., TGFß)." (PMID 35845058, 2022). "miRNA-99a directly targets mTOR, inhibiting cell apoptosis and increases autophagy through the mTOR/P70/S6K signaling pathway, and improving the cardiac function and survival rate in a mouse model of myocardial infarction." (PMID 35370737, 2022). "Overall depletion of B cells reduces the infarct size in models of myocardial infarction which could be reached by mTOR inhibition to repress B cell development." (PMID 35845058, 2022). "Moreover, lncRNA myocardial infarction associated transcript (MIAT) promotes CC and up-regulates PI3K, AKT, and mTOR levels, indicating its ability to activate PI3K/AKT/mTOR signaling pathway." (PMID 34703793, 2021). "We hypothesized that Rapamycin, given at the onset of reperfusion, reduces myocardial infarct size through modulation of mTOR complexes." (PMID 28373901, 2017). "In the postinfarct heart, cardiac BCAA catabolism is impaired, resulting in myocardial BCAA accumulation; then, BCAAs activate myocardial mTOR signaling and subsequently contribute to cardiac dysfunction and remodeling following myocardial infarction (MI)." (PMID 35911554, 2022).
myocardial infarction (continued). "Moreover, the activation of autophagy by mTOR inhibitors or other autophagy enhancers may reduce the area of the myocardial infarct and mitigate left ventricular remodeling after myocardial infarction." (PMID 33328993, 2020). "In the present study, clinically relevant dose of Rapamycin attenuated cardiac dysfunction and adverse remodeling after myocardial infarction in vivo and in vitro, which provided evidence that the mTOR inhibitor Rapamycin could be used for preventing LV remodeling after AMI." (PMID 25409294, 2014). "Injecting MSC-derived exosomes into rats that had undergone AMI markedly decreased the apoptosis rate of MSCs and reduced the myocardial infarct size via upregulating myocardial LC3B expression and activating the AMPK/mTOR and AKT/mTOR pathways." (PMID 30995935, 2019). "In a rat MI/R model, injection of BMSC-derived exosomes reduced apoptosis and myocardial infarct size and subsequently improved heart functions by inducing cardiomyocyte autophagy via AMPK/mTOR and Akt/mTOR pathways." (PMID 29904347, 2018). "Reduced apoptosis and myocardial infarct size and subsequently improved heart functions by inducing cardiomyocyte autophagy via AMPK/mTOR and Akt/mTOR pathways." (PMID 29904347, 2018). "Pharmacological mTOR inhibition by rapamycin has been shown to improve cardiac function in PO LVH, after myocardial infarct, in a LEOPARD syndrome model and after kidney transplantation." (PMID 26306297, 2015). "For instance, NLRP3 inflammasome knockout in endothelial progenitor cells (EPCs) was reported to rescue angiogenesis in diabetic mice with myocardial infarction, suggesting that the PI3K/AKT/mTOR cascade acts as a downstream effector of NLRP3-mediated inflammatory responses." (PMID 40313483, 2025). "In myocardial infarction, it could be assumed, that a decrease of CD8+ T cells by mTOR inhibition could lower apoptosis." (PMID 35845058, 2022). "In another research on a model of myocardial ischemic injury, exosomes from BM-derived mesenchymal stem cells reduced apoptosis and the size of myocardial infarction and, after that, recovered heart function by persuading cardiac autophagy via two pathways such as AMPK/mTOR and Akt/mTOR routes." (PMID 35550188, 2022). "In vivo experiments showed that CASR could significantly improve myocardial infarction, blood stasis, and blood lipid levels and regulate the PI3K/AKT/mTOR signaling pathway in CHD rats." (PMID 36016561, 2022). "In a rat myocardial ischaemia reperfusion injury model, injection of bone marrow-derived MSCs-derived exosomes reduced apoptosis and myocardial infarct size and subsequently improved heart functions by inducing cardiomyocyte autophagy via AMPK/mTOR and Akt/mTOR pathways." (PMID 30992990, 2019). "Given that ROS-induced autophagy and subsequent ferroptosis may contribute to myocardial injury after a heart attack, idebenone attenuates ferroptosis by inhibiting excessive autophagy through the ROS/AMPK/mTOR pathway to preserve cardiac function post-infarction." (PMID 38169754, 2024). "However, deletion of CD8+ cells was not beneficial for the outcome after myocardial infarction and even induced a rupture of the ventricle due to inadequate clearing of necrotic material indicating deleterious effects of overly inhibited mTOR signaling." (PMID 35845058, 2022).
ischemia (72 papers, 2012 to 2025). A hypoperfusion of the BLOOD through an organ or tissue caused by a PATHOLOGIC CONSTRICTION or obstruction of its BLOOD VESSELS, or an absence of BLOOD CIRCULATION. "Other studies have shown that the AMPK/mTOR pathway is activated by Serpinb1a overexpression in ischemia models and that upstream ADAM causes AKT activation." (PMID 38338984, 2024). "As a tissue with extremely high nutritional demands, the brain is susceptible to metabolic dysregulation following ischemia, particularly through the abnormal activation of the mTOR pathway." (PMID 40789569, 2024). "MTOR-dependent signal transduction is implicated in cardiac remodeling, and an mTOR inhibitor has been verified to augment autophagy and limit the infarct size of ischemia myocardium." (PMID 35273164, 2022). "Another important aspect is that during ischemic cardiac injury, the activation of the mTOR pathway may play a protective role against oxidant injury caused by ischemia/reperfusion in cardiac myocytes." (PMID 27880847, 2016). "We focused our research on the characterization of caffeine as a potential treatment and elucidated how caffeine affects the AMPK/mTOR pathway as a potential target for the neuroprotective effect observed after treatment in a neonatal hypoxia-ischemia model." (PMID 39744433, 2025). "In other words, in the cerebral cortex of elderly individuals, ischemia induces a pathological predominance of the Akt/FOXO3a axis with relative insufficiency of Akt/mTOR signaling." (PMID 41515961, 2025). "Concurrently, ischemia-induced zinc accumulation disrupts mitochondrial integrity, promotes excessive ROS production, and triggers maladaptive autophagy via mTOR inhibition and oxidative stress enhancement, thereby intensifying neuroinflammatory cascades." (PMID 41007413, 2025). "An integrated approach to understanding ischemia-induced molecular mechanisms of regulation of the mTOR signaling pathway, including the involvement of αKG, can increase the effectiveness of exogenous neuroprotection in ischemia-induced disorders." (PMID 37252190, 2023). "Induction of autophagy was also found in hippocampal CA1 cells in a rat model of global ischemia by a decrease of intracellular concentration of mammalian target of rapamycin (mTOR)." (PMID 36219377, 2023). "One study showed that the activation of PI3K-Akt-mTOR signaling pathway can promote mitochondrial fusion and suppress mitochondrial fission, thus attenuating ischemia-reperfusion injury in diabetic cardiomyopathy." (PMID 36788223, 2023). "In the tMCAo model, mTORC1 and mTORC2 activity suppression using Rapalink-1, a third-generation mTOR inhibitor, has been reported to exacerbate neuronal damage induced by ischemia in the short-term, worsen BBB stability, and increase the area of damage." (PMID 35269956, 2022). "Another study indicated that canonical AMPK- and Akt-mTOR-mediated autophagy had a myocardial protective effect during ischemia and reperfusion." (PMID 36017337, 2022). "Using tMCAo rats, it has been shown that early downregulation of the Akt/mTOR/STAT3 pathway after ischemia suppresses microglia-mediated neuroinflammation and improves cerebral injury." (PMID 35269956, 2022). "The mechanistic target of rapamycin (mTOR) promotes the expression of TfR1 and ferroportin and alters cellular iron flux to protect the heart against pathological stimuli such as ischemia." (PMID 33532140, 2021). "Recent studies report crosstalk between HIPPO signaling and mTOR pathway, and it is shown that Akt is one of mTORC1 activators in cardiac fibroblasts post ischemia." (PMID 34200497, 2021). "Inhibition of GSK-3β has also been confirmed to stimulate the mTOR pathway in the heart during ischemia/reperfusion." (PMID 34298987, 2021). "Compared with the vehicle control, metformin administration to aging mice markedly increased the myocardial phosphorylation of AMPK, whereas phosphor‐mTOR (p‐mTOR) levels decreased during ischemia." (PMID 31944526, 2020).
ischemia (continued). "Together, these results suggest that the modulating effects of AMPK/mTOR/ULK1 signaling on endogenous autophagy were weakened on day 3 after ischemia, whereas DADLE-mediated DOR activation augmented autophagy by triggering AMPK/mTOR/ULK1 signaling." (PMID 32549974, 2020). "In the heart, AMPK- and mTOR-dependent autophagy are part of the cardioprotective effects during ischemia." (PMID 32656262, 2019). "In the ND 2-min TI group, mTOR and p-mTOR levels were significantly increased (about 1.6-fold, p < 0.05, and 1.7-fold, p < 0.05 of the ND sham group, respectively) at 2 days post-ischemia, and each level was maintained until 5 days post-ischemia." (PMID 31546722, 2019). "In this context, our data were in accordance with earlier results of Liu and colleagues, who showed that MSC-derived exosomes significantly reduced the expression of phosphorylated mTOR/mTOR in rat cardiomyocytes after ischemia reperfusion injury." (PMID 30467302, 2018). "Mechanistically, the protective effect of HSYA in alleviating myocardial injury after ischemia may be associated with NLRP3 inflammasome, Bcl-2, Bax, caspase-3, eNOS proteins, and TLR/NF-κB, Nrf2/HO-1, JAK/STAT, PI3K/Akt, AMPK/mTOR, VEGFA pathways." (PMID 40271057, 2025). "Likewise, microglial exosome–derived miR-124-3p, validated in traumatic brain injury models, suppresses STAT3-dependent mTOR activation, thereby enhancing mitophagic clearance of damaged mitochondria and promoting M2-like microglial polarization in ischemia." (PMID 41007413, 2025). "Without NLRX1 present, the energy sensor AMPKα is continuously activated in the heart, thereby preventing mTOR and RISK pathway activation during early reperfusion of the ischemic hearts, contributing to the increased sensitivity of the heart to ischemia–reperfusion injury." (PMID 40536683, 2025). "According to the enrichment results, mTOR pathways were continuously activated during 5 minutes and 5 days after ischemia, indicating that mTOR may be an important factor in myocardial I/R injury." (PMID 35419165, 2022). "These seemingly contradictory results regarding the positive effects of either activation or inhibition of mTOR in neurons in the context of ischemia may be explained by the doses and time points selected for the analysis." (PMID 35269956, 2022). "Additionally, the activation of PDK1-Akt-mTOR-p70S6K reduces injury during ischemia and reperfusion of the liver." (PMID 34064340, 2021). "The mTOR pathway is involved in brain injury induced by ischemia." (PMID 34900085, 2021). "These in vivo results indicate that the effect of DADLE against ischemia could be attributed to a DOR/AMPK/mTOR/ULK1 signaling pathway-dependent increase in autophagic activity." (PMID 32549974, 2020). "Besides, the ratio of LC3-II to LC3-I has been found to be reduced when the mTOR axis was activated, preventing against myocardial injury during the acute stage of ischemia/reperfusion injury." (PMID 31168354, 2019). "Conversely, we observed decreased levels of p-Akt Ser473, p-mTOR Ser2448, and mTOR activity concomitant with the decline of tauopathy and neuronal loss at 30 days post-ischemia in the absence of changes in Bcl-2 protein levels, suggesting apoptotic regulation." (PMID 26042033, 2015). "As the intestinal epithelium displays rapid cell growth and differentiation and is an important immune regulatory organ, we hypothesized that mTOR may play an important role in the protection against intestinal ischemia reperfusion (I/R)-induced injury." (PMID 22848534, 2012). "Similarly, crocin was found to suppress excessive autophagy and activate Akt during reperfusion, suggesting its bidirectional regulation of autophagy through both the AMPK/mTOR and Akt/mTOR signaling pathways, thereby exerting a protective effect against ischemia-reperfusion injury." (PMID 40491718, 2025).